FATE1 (fetal and adult testis expressed 1)
Description:
Involved in the regulation of endoplasmic reticulum (ER)- mitochondria coupling. Negatively regulates the ER-mitochondria distance and Ca(2+) transfer from ER to mitochondria possibly implicating it in the regulation of apoptosis. May collaborate with RNF183 to restrain BIK protein levels thus regulating apoptotic signaling.
Synonyms: CT43; FATE
Tractability: Antibody: UniProt predicts a signal peptide or a membrane-spanning region.
Gene: Protein-coding gene on chromosome X (151,714,192 to 151,723,194, forward strand). Ensembl gene ENSG00000147378.
Subcellular location: Mitochondrion; Mitochondrion outer membrane; Endoplasmic reticulum membrane
Gene Ontology:
Molecular function: identical protein binding; protein binding; ubiquitin protein ligase binding
Biological process: negative regulation of apoptotic process; negative regulation of mitochondrial calcium ion concentration; regulation of apoptotic process
Cellular component: endoplasmic reticulum; endoplasmic reticulum membrane; mitochondria-associated endoplasmic reticulum membrane contact site; mitochondrial outer membrane; mitochondrion; cytoplasm
Homologues: Orthologues: chimpanzee FATE1 (99% identical), macaque FATE1 (94% identical), dog FATE1 (67% identical), pig FATE1 (54% identical), mouse Fate1 (26% identical).
Diseases named in the same sentence as FATE1 in open-access papers:
FATE1 is named in the same sentence as 15 diseases in open-access papers, as found by Europe PMC text mining. Sharing a sentence is not in itself a finding about the gene and the disease. The quoted sentences say what the papers report.
adrenocortical carcinoma (4 papers, 2017 to 2023). "In adrenocortical carcinoma, fetal and adult testis-expressed 1 (FATE1), which encodes a cancer-testis antigen has been shown to localise to MAMs." (PMID 37426575, 2023). "The SF-1 transcription factor target gene FATE1 encodes a cancer-testis antigen that has an important role in regulating apoptosis and response to chemotherapy in adrenocortical carcinoma (ACC) cells." (PMID 32183347, 2020). "Collectively these data highlight that FATE1 plays a key role in the aggressive phenotype of adrenocortical carcinoma and is also implicated in the resistance to chemotherapeutic treatments in other kinds of cancer." (PMID 33233365, 2020). "Of note, FATE1 expression is low in normal adrenal cortex and in benign tumors (hyperplasia and adenoma), but is overexpressed in adrenocortical carcinoma." (PMID 33233365, 2020). "In addition, Furthermore, FATE1 has also been suggested to attenuate apoptosis in these adrenocortical carcinoma cells." (PMID 37426575, 2023). "Moreover, FATE1 expression is also inversely correlated with the overall survival of adrenocortical cancer patients." (PMID 28516062, 2017).
adrenocortical tumors (2 papers, 2020 to 2021). "Our results show that patients with adrenocortical tumors (both benign and malignant) can mount an immune response against FATE1, as shown by the widespread presence of circulating antibodies directed against this cancer-testis antigen." (PMID 32183347, 2020). "In this study, we investigated the prevalence of circulating anti-FATE1 antibodies in pediatric and adult patients with adrenocortical tumors using three different methods (immunofluorescence, ELISA and Western blot)." (PMID 32183347, 2020). "Patients with adrenocortical tumors had high tumor FATE1 mRNA expression levels and could mount an immune response against FATE1, as shown by the widespread presence of circulating antibodies directed against this cancer-testis antigen." (PMID 33672007, 2021). "The presence of circulating antibodies directed against FATE1 was assessed in a cohort of adult patients with adrenocortical tumors from three different ENSAT centers (46 malignant—among these, six patients had a pre-surgery and a post-surgery sample available for analysis—and 10 benign)." (PMID 32183347, 2020).
osteosarcoma (2 papers, 2020 to 2021). A usually aggressive malignant bone-forming mesenchymal neoplasm, predominantly affecting adolescents and young adults. "Recently, it has been found that the risk model composed of CD180, MYC, PROSER2, and FATE1 has a great fitting effect on the overall lifetime of osteosarcoma." (PMID 34488541, 2021). "Among them, five genes, including CD180, MYC, PROSER2, DNAI1, and FATE1, with significant contribution to the model were selected as the candidate genes in the optimal prognostic risk model of osteosarcoma." (PMID 33082842, 2020).
Ewing sarcoma (1 paper, 2020). A small round cell tumor that lacks morphologic, immunohistochemical, and electron microscopic evidence of neuroectodermal differentiation. "However, in Ewing sarcoma cells, no appreciable levels of BIK protein are detectable even in the presence of the proteasome inhibitor MG132, and FATE1 depletion does not induce BIK accumulation." (PMID 32486221, 2020).
hepatocellular carcinoma (1 paper, 2020). A malignant tumor that arises from hepatocytes. "Autoantibodies directed against FATE1 were previously detected in patients with hepatocellular carcinoma." (PMID 32183347, 2020).
Insulin resistance (1 paper, 2019). Increased resistance towards insulin, that is, diminished effectiveness of insulin in reducing blood glucose levels. "In addition, disruption of MAMs by FATE-1 blunted the impact of NO on insulin signaling, causing insulin resistance." (PMID 31731523, 2019).
kidney cancer (1 paper, 2022). Primary or metastatic malignant neoplasm involving the kidney. "We observed that the mRNA expression level of ETV4 was significantly increased and the expression levels of SH2B3, FATE1, GRK5, MALL, HRH2, SEMA3G and SLC10A6 were decreased prominently in kidney cancer cells when compared with HK2 cell line." (PMID 36059531, 2022). "Furthermore, we detected the mRNA and protein expression levels of 8 epi-PCGs (ETV4, SH2B3, FATE1, GRK5, MALL, HRH2, SEMA3G and SLC10A6) in 4 human kidney cancer cell lines (786-O, A498, Caki-1 and ACHN) and the normal human renal tubular epithelial cell line HK2." (PMID 36059531, 2022).
melanoma (1 paper, 2015). A malignant, usually aggressive tumor composed of atypical, neoplastic melanocytes. "Depletion of FATE1 led to a>30% reduction of viability in melanoma, breast, prostate andsarcoma settings." (PMID 26567849, 2015).
metastatic disease (1 paper, 2022).
renal clear cell carcinoma (1 paper, 2021). "Here, using single-cell RNA sequencing of immune cells from renal clear cell carcinoma (ccRCC) patients, we identify two distinct transcriptional fates for TI Treg cells, Fate-1 and Fate-2." (PMID 34599187, 2021).
sarcoma (1 paper, 2015). A usually aggressive malignant neoplasm of the soft tissue or bone. "Given this broad penetrance, we further evaluated thetumour cell dependency on FATE1 by expanding our analysis to additional celllines derived from colorectal, ovarian, sarcoma, breast, cervical and NSCLCcancers." (PMID 26567849, 2015).
testicular cancer (1 paper, 2020). A primary or metastatic malignant neoplasm that affects the testis. "Fetal and adult testis expressed 1 (FATE-1) is a testicular cancer antigen that is involved in uncoupling ER-mitochondria interactions and disrupting Ca2+ transfer from the ER to mitochondria, suggesting that it plays a role in regulating apoptosis." (PMID 32766245, 2020).
cancer (11 papers, 2003 to 2023). A tumor composed of atypical neoplastic, often pleomorphic cells that invade other tissues. "In addition to DNAI1, another three genes, MYC, PROSER2, and FATE1, have been reported to be associated with several cancers." (PMID 33082842, 2020). "However, in certain cancers, FATE1 becomes upregulated and causes MAMs alterations." (PMID 29491433, 2018). "This was proposed as a possible mechanism of how FATE1 can contribute to chemotherapeutic resistance in cancer cells." (PMID 36980267, 2023). "In normal tissues, the expression of FATE1 is mainly restricted to the testis and adrenal glands, and its expression is up-regulated in a variety of cancers." (PMID 36059531, 2022). "FATE1 is one of the cancer/testis antigens whose expression is biased to the testes but is also activated in cancer." (PMID 32486221, 2020). "FATE1 belongs to the group of cancer-testis antigens, proteins whose expression is restricted to the gonads in the physiological setting, while it is reactivated in several tumor types." (PMID 32183347, 2020). "Upregulation of FATE1 in cancers may occur to drive uncoupling of the ER and mitochondria, attenuate Ca2+ delivery and increase the resistance to cell death in these cancer cells." (PMID 37426575, 2023). "FATE1 mRNA expression is preponderant in ACC among all malignancies in the TCGA pan-cancer dataset." (PMID 32183347, 2020). "Regarding strategies used to disrupt MAMs, manipulation of FATE1 expression might be the preferred alternative, because FATE1 expression is mainly restricted to the testis, adrenal gland, and in a variety of cancers." (PMID 32952849, 2020). "Moreover, Maxfield and coworkers showed that FATE1 inhibits proapoptotic signaling in different cancer cell lines, by destabilizing the pro-apoptotic BCL2 interacting killer (BIK) protein." (PMID 33233365, 2020). "In this way, FATE1 protects cancer cells from Ca2+-dependent apoptotic stimuli." (PMID 29491433, 2018). "The interaction of FATE1 with the E3 ligase RNF183 induced BIK (a BH3-only pro-apoptotic protein) degradation and subsequent resistance to apoptotic signals in cancer cells." (PMID 36980267, 2023). "On the other hand, FATE1 expression in the most aggressive group of ACC could open new perspectives for immunotherapy using vaccination against this and other cancer neoantigens." (PMID 33672007, 2021). "Additionally, FATE1 silencing increased sensitivity of the NCI-H1155 non-small lung cancer cell line to paclitaxel and reduced viability of a variety of other cancer cell lines." (PMID 32183347, 2020). "Furthermore, oncogenes like Akt/PKB and FATE1, and tumor suppressors like PML and PTEN, can play additional roles in the development of cancer via Ca2+-signaling modulation." (PMID 29491433, 2018). "On the other side, FATE1 expression in the most aggressive group of ACC could open new perspectives for immunotherapy using vaccination against this and other cancer neoantigens, possibly in combination with steroidogenic inhibitors to counteract the immunosuppressive action of glucocorticoids." (PMID 32183347, 2020). "Additionally, FATE1 could be relevant also in other tumors as it has been reported that its silencing increased sensitivity of the NCI-H1155 NSLC cell line to paclitaxel and reduced the viability of a variety of other cancer cell lines." (PMID 33672007, 2021).
tumor (5 papers, 2003 to 2021). "High tumor FATE1 mRNA expression levels in adult ACC are associated with high steroidogenic gene expression, immune cell depletion and worse prognosis." (PMID 32183347, 2020). "In multivariate analysis, pathological tumor size remained significant and FATE1 expression tended towards significance." (PMID 32183347, 2020). "Only patients expressing FATE1 mRNA in the tumor had circulating anti-FATE1 antibodies detectable using ELISA or Western blot." (PMID 32183347, 2020). "FATE1 expression was in most cases inhomogeneous in the tumors, with groups of FATE1-positive cells being intermingled with FATE1-negative tumor tissue." (PMID 32183347, 2020). "To examine the consequences of FATE1 expression in patient tumours, we examinedthe Cancer Genome Atlas (TCGA) colorectal data set, given that depletion ofFATE1 was most potent in the HCT116 colorectal cell line." (PMID 26567849, 2015). "The frequency of co-expression of RNF183 and FATE1 alongwith their correlation with poor outcome reinforces the notion that theseproteins are functioning in human tumours to promote survival." (PMID 26567849, 2015). "In multivariate analysis, only pathological tumor size and FATE1 expression remained significant." (PMID 32183347, 2020). "Interestingly, FATE1 expression in ACC tumor cells can even be used as a prognosis indicator since FATE1 expression is inversely correlated with the overall survival of ACC patients." (PMID 29491433, 2018). "FATE1 may represent one mechanism by which tumour cellsovercome these barriers by promoting the degradation of second messengers in thissignalling system." (PMID 26567849, 2015). "In the cleavedcaspase-3/7 survival screen, depletion of FATE1 elevated the activity of theseexecutioner caspases greater than twofold, a phenotype that was also detectableby immunoblot in a range of tumorigenic settings and suggests that FATE1 isessential for tumour cell survival." (PMID 26567849, 2015).
FATE1 also shares sentences with these, for which no sentence is quoted: liver cirrhosis (1 paper).